SMG9 (SMG9 nonsense mediated mRNA decay factor)
Description:
Involved in nonsense-mediated decay (NMD) of mRNAs containing premature stop codons. Is recruited by release factors to stalled ribosomes together with SMG1 and SMG8 (forming the SMG1C protein kinase complex) and, in the SMG1C complex, is required for the efficient association between SMG1 and SMG8. Plays a role in brain, heart, and eye development (By similarity).
Synonyms: C19orf61; FLJ12886; F17127_1; HBMS; NEDITPO
Tractability: Small molecule: a structure with a bound ligand is known. PROTAC: ubiquitination databases record sites on it; its protein half-life has been measured.
Gene: Protein-coding gene on chromosome 19 (43,727,983 to 43,755,054, reverse strand). Ensembl gene ENSG00000105771.
Subcellular location (Human Protein Atlas): Cytosol; Vesicles
Pathways (Reactome):
Metabolism of RNA: Nonsense Mediated Decay (NMD) enhanced by the Exon Junction Complex (EJC)
Gene Ontology:
Molecular function: identical protein binding; protein binding
Biological process: negative regulation of apoptotic process; nuclear-transcribed mRNA catabolic process, nonsense-mediated decay; brain development; eye development; heart development; regulation of nuclear-transcribed mRNA catabolic process, nonsense-mediated decay
Cellular component: serine/threonine protein kinase complex; cytosol
Genetic constraint (gnomAD): Loss-of-function variants: 51 observed, 61.34 expected, observed/expected ratio (o/e) 0.83, 90% interval 0.66 to 1.05. The upper end of that interval is the gene's LOEUF score, 1.05, which puts it in group 4 of 6, group 1 being the genes least tolerant of losing a copy. Missense variants: 553 observed, 691.47 expected, observed/expected ratio (o/e) 0.8, 90% interval 0.75 to 0.86. Synonymous variants: 243 observed, 257.33 expected, observed/expected ratio (o/e) 0.94, 90% interval 0.85 to 1.05.
Homologues: Orthologues: chimpanzee SMG9 (100% identical), dog SMG9 (98% identical), guinea pig SMG9 (97% identical), mouse Smg9 (97% identical), rabbit SMG9 (96% identical), rat Smg9 (96% identical), macaque SMG9 (96% identical), pig SMG9 (92% identical), tropical clawed frog smg9 (73% identical), zebrafish smg9 (72% identical), Drosophila melanogaster CG3857 (23% identical), Caenorhabditis elegans smg-9 (19% identical).
Diseases named in the same sentence as SMG9 in open-access papers:
SMG9 is named in the same sentence as 24 diseases in open-access papers, as found by Europe PMC text mining. Sharing a sentence is not in itself a finding about the gene and the disease. The quoted sentences say what the papers report.
Intellectual disability (3 papers, 2022). "The most frequent characteristic features of these subjects with SMG9-deficiency are facial dysmorphism, congenital heart defects, severe intellectual disability, growth restriction, microcephaly and brain abnormalities." (PMID 35321723, 2022). "Homozygous loss-of-function variants in the SMG9 gene (OMIM: 613176) were recently described to cause a neurodevelopmental disorder characterized by intellectual disability and multiple malformations in twelve affected individuals from worldwide." (PMID 35321723, 2022). "In summary, we identified a novel compound heterozygous variant in the SMG9 gene in two patients from the same family with a degree of intellectual disability, developmental delay, and other congenital abnormalities." (PMID 35321723, 2022). "The patients showed the common phenotypes associated with SMG9-deficiency syndrome, including facial dysmorphism, a degree of intellectual disability, developmental delay, mild generalized brain atrophy, and congenital heart defects." (PMID 35321723, 2022). "The most frequent manifestations of these subjects with mutations in the SMG9 gene are microcephaly, cerebral malformations, intellectual disability, congenital heart defects, and ocular anomalies." (PMID 35321723, 2022). "Herein, whole exome sequencing was performed to identify novel compound heterozygous SMG9 variants (NM_019108.3: c.1318_1319delAG (p.Ser440*) and c.947A>G (p.His316Arg)) in the proband, who exhibited syndromic intellectual disability." (PMID 35321723, 2022). "Interestingly, in patients with neurocognitive impairment, SMOX over-expression caused by SMG9 Nonsense Mediated MRNA Decay Factor (SMG9) loss-of-function, a gene key regulator of nonsense-mediated decay, was associated with intellectual disability." (PMID 35885061, 2022).
developmental delay (2 papers, 2022 to 2023). "Deletion or mutation of the SMG9 gene can result in severe developmental anomalies, including malformations or overgrowth of the brain, heart, face, or eyes, and developmental delay." (PMID 37889708, 2023).
anorexia nervosa (1 paper, 2025). A disorder most often seen in adolescent females characterized by a refusal to maintain a minimally normal body weight, an intense fear of gaining weight, a disturbance in body image, and, in postmenarcheal females, the development of amenorrhea. "In addition, SMG9 in AD, TCTA in anorexia nervosa, RHOA and IMPDH2 in intelligence, CRHR1 in PD, and PHF7 in schizophrenia are all reported to be conserved among a wide range of species, although their relations with the corresponding traits remain to be explored." (PMID 39905509, 2025).
chronic myelogenous leukemia (1 paper, 2022). "ATRi resistance within the context of SMG8 or SMG9 deficiency was not unique to the YCC6 cells; SMG8 or SMG9 mutant HAP1 cells (chronic myelogenous leukemia cells with homozygous premature truncating mutations and loss of WT protein) were also resistant to ATRi." (PMID 36273494, 2022).
heart and brain malformation syndrome (1 paper, 2022). "SMG9-deficiency syndrome, also known as heart and brain malformation syndrome, is a very rare congenital genetic disorder mainly characterized by brain, heart, and growth and developmental abnormalities." (PMID 35321723, 2022).
hepatocellular carcinoma (1 paper, 2021). A malignant tumor that arises from hepatocytes. "However, little is known about the role of SMG9 in hepatocellular carcinoma (HCC)." (PMID 34456727, 2021).
liver cancer (1 paper, 2021). An epithelial or non-epithelial malignant neoplasm that arises from the liver. "Accordingly, understanding the other potential functions of SMG9 during HCC progression is an attractive direction for future work, which will provide a new strategy for liver cancer prevention and treatment." (PMID 34456727, 2021).
infection (2 papers, 2020 to 2023). The state of being infected such as from the introduction of a foreign agent such as serum, vaccine, antigenic substance or organism. "NMD inhibition (+U1D) and PEMV2 infection resulted in increased transcript levels for SMG7, SMG9, UPF1, UPF3, and CASC3, whereas HA-p26 expression increased transcript levels only for SMG7, SMG9, and UPF3." (PMID 32156817, 2020).
neurodevelopmental disorder (2 papers, 2022). A behavioral and cognitive disorder with onset during the developmental period that involves impaired or aberrant development of intellectual, motor, or social functions. "In conclusion, we demonstrate that the SMG9 c.551T > C missense variant causes a neurodevelopmental disorder and impacts gene expression." (PMID 35087184, 2022). "For instance, loss-of-function mutations in UPF2, UPF3B, SMG8 and SMG9 genes, and CNVs targeting UPF2, UPF3A, SMG6, EIF4A3, RNPS1 and RBM8A genes, have been implicated in a variety of neurodevelopmental disorders, including DD, ID, ADHD and TAR syndrome." (PMID 35327467, 2022).
cancer (1 paper, 2025). A tumor composed of atypical neoplastic, often pleomorphic cells that invade other tissues. "In particular, the cancer-derived mutations within SMG1 located at 248–910 and 2200–2400 amino acids were evaluated in terms of the change in affinity or stability in the presence of SMG8/SMG9 and UPF1, respectively." (PMID 41189592, 2025). "In addition, the effect of cancer-derived mutations in SMG1 (located within 248 aa–910 aa and 2,200 aa–2,400 aa) was characterized, and their effects on the binding affinity and stability in the presence of SMG8, SMG9, and UPF1 were predicted." (PMID 41189592, 2025).
tumor (1 paper, 2021). "The expression level of SMG9 was significantly associated with tumor number (p = 0.014), tumor size (p = 0.015), and TNM stage (p = 0.025)." (PMID 34456727, 2021). "SMG9 mRNA level was measured in sixteen sets of fresh tumor tissues and adjacent non-cancerous liver tissues (ANLTs) via reverse transcription-quantitative polymerase chain reaction (RT-qPCR)." (PMID 34456727, 2021).
SMG9 also shares sentences with these, for which no sentence is quoted: brain abnormalities (1 paper); colorectal tumor (1); congenital heart defects (1); dyspraxia (1); generalized brain atrophy (1); glioma (1); growth (1); hereditary coproporphyria (1); microcephaly (1); osteoarthritis (1); preeclampsia (1); schizophrenia (1); variegate porphyria (1).